TNF (tumor necrosis factor)
Diseases named in the same sentence as TNF in open-access papers (continued):
Sharing a sentence is not in itself a finding about the gene and the disease.
COVID-19 (continued). "In addition, regardless of whether PD patients had COVID-19, the levels of TNF-α and IL-17 were greater in PD patients than in HCs, whereas the level of IL-4 was lower in PD patients than in HCs." (PMID 40292283, 2025). "Notably, none of the COVID-19 patients who died presented high levels of TNF-α." (PMID 40508859, 2025). "Furthermore, according to Kyoto Encyclopedia of Genes and Genomes (KEGG) pathway analysis, it is proposed that quercetin may treat COVID-19-induced AKI through various pathway interactions such as TLR, HIF-1α, vascular endothelial growth factor (VEGF), TNF, and apoptosis." (PMID 39126050, 2024). "Furthermore, while systemic increases in IL-1β, IL-6, TNF-α, and IFN-γ have traditionally been viewed as immunopathological hallmarks of acute COVID-19, most of these cytokines, along with several markers of brain injuries, have recently emerged as potential biochemical indicators of long COVID-19." (PMID 38338174, 2024). "We analyzed the frequencies of the two polymorphisms in the control groups (CG: TNF -308G/A, n = 497; IFNG +874T/A, n = 397), a group of patients with COVID-19 (CoV, n = 222) and among the subgroups of patients with nonsevere (n = 150) and severe (n = 72) COVID-19." (PMID 38675991, 2024). "Furthermore, TNF and VEGFA, which exhibited higher degree values in target prediction and network construction, may also play significant roles in Danshen's therapeutic effects against COVID-19." (PMID 38834599, 2024). "The severity of COVID-19 is often accompanied by IFN-Is response, in addition to the TNF/IL-1β response, indicating that the IFN-I response could aggravate the hyper-inflammatory response by strengthening TNF/IL-1β-driven inflammation, thus influencing the severe progression of COVID-19." (PMID 38124132, 2023). "Intestinal dysbiosis in some COVID-19 patients may contribute to the translocation of LPS from intestine into the portal circulation, hence stimulating the Kupffer cells in the liver and leading to the activation of NF-κB signaling and release of IFN-β and TNF-α." (PMID 38156008, 2023). "Moreover, levels of CRP, IL-6, IL-8, IL-10, tumor necrosis factor (TNF)-α and IL-2R showed a positive correlation with high-sensitivity cardiac troponin I, consistent with the contribution of the inflammatory response to cardiac injury present in COVID-19 patients." (PMID 37168848, 2023). "Moreover, anti-TNFα (tumor necrosis factor) and Jak (Janus kinase)-inhibitors used in RA are effective for controlling ACE2 expression, which may contribute to prevention of infections and/or severe forms induced by COVID-19." (PMID 35434592, 2022). "However, the inflammatory response in COVID-19 still shares some common signatures with the inflammatory response in LPS-induced RAW264.7 cells, among which the most typical are TLR4, NF-κB, and other signaling pathways and their corresponding cytokines (including IL-6, TNF, IL-1β, etc.)." (PMID 35669076, 2022). "The presence of cytoplasmic IFN-γ and TNF-α proteins, measured ex vivo, highly correlated with cell membrane expression of CD49a, CD69, and CD107a, raising the question whether these CD69+CD49a+CD107a+ cytokine-producing NK cells in severe COVID-19 patients represent a distinct subset of NK cells." (PMID 36275702, 2022). "Importantly, the prognosis from COVID-19 patients with severe illness is linked with the lower concentrations of several inflammatory cytokines including ICAM, TNF-α, and CRP, suggesting that ICAM might display an important role in the pathogenesis of COVID-19." (PMID 36290585, 2022). "Similarly, activation of COX2 and HIF-1α in COVID-19 has been shown to upregulate the antiapoptotic antiproliferative microenvironment (BCL2, BNIP3) and M1 immune system {nuclear factor kappa B (NFKB), Egl-9 family hypoxia inducible factor 3 (EGLN3), CXCL8, TNF-α, and IL-6 }." (PMID 36671699, 2022).
COVID-19 (continued). "LXA4 attenuates liver fibrosis by suppressing TNF-α, IFN-γ, IL-2, and IL-17 and augmenting IL-4 and IL-10 production, implying that LXA4 and its precursor AA may be of benefit in preventing the lung fibrosis seen in some patients with COVID-19 (termed as long-haulers)." (PMID 34944517, 2021). "Interestingly, the p38 MAPK inhibitor reduced the gene expression levels of TNF-α and other inflammatory cytokines that were increased during the SARS-CoV-2 infection of lung cancer cells in a dose-dependent manner, referring to p38 MAPK as a potential pharmacological target for COVID-19." (PMID 33995033, 2021). "Moreover, the correlation coefficients for IL-4 and IL-2, IL-4 and TNF-α, and NK cells and T cells were the lowest in nonmetastatic patients, followed by metastatic and nonsevere COVID-19 patients, and were the highest in severe COVID-19 patients." (PMID 34712741, 2021). "Interestingly, different from the ARDS phenotypes, we observed that none of inflammatory cytokines could predict COVID-19 phenotypes, except for TNF-α." (PMID 34150812, 2021). "First, some inflammatory markers (such as ferritin, TNF-α, and IL-6) that were confirmed to be elevated during cytokine storm in patients with severe COVID-19 may not be available in most grassroots hospitals or laboratories in developing countries and are mainly used for research purposes." (PMID 34900028, 2021). "Furthermore, it has also been demonstrated that COVID-19 patients are markedly characterized by elevated serum levels of pro-inflammatory cytokines; for instance, interleukin (IL)-1, IL-6, IL-12, interferon-gamma (IFN-γ) and tumor necrosis factor-alpha (TNF-α)." (PMID 38624830, 2021). "An ex vivo study of NK cells from the peripheral blood of patients with COVID-19 revealed a decrease in the expression of CD107a, caspase Ksp37, granzyme B, and granulysin; these changes could result in reduced cytotoxicity and insufficient production of IFN-γ and TNF-α." (PMID 34603758, 2021). "Furthermore, we have demonstrated in vitro efficacy of NIC-hLYS reducing complications related to COVID-19, most notably secondary bacterial pneumonia by MRSA and dampening (but not complete suppression) of TNF-α and IL-6, which are known markers for COVID-19 disease severity." (PMID 33571320, 2021). "Notably, we observed that the classical monocytes and myeloid cells from severe COVID-19 patients in the single-cell RNA-seq data expressed high levels of S100A12, the gene encoding EN-RAGE, but not the typical inflammatory molecules IL-6 and TNF-α." (PMID 32788292, 2020). "Taken together, our findings may assist future management of COVID-19 patients, as they may exhibit diverse expression profiles of molecular regulators such as DANCR and NEAT1, in conjunction with previously depicted inflammatory mediators such as IL-1, IL-6, TNF, and more." (PMID 33163005, 2020). "We believe that targeting the central pathway (IL-1β, TNF-α, IL-6), balancing the Th1 and Th2 response, and administering long-term anti-inflammatory therapy might be promising prospects to reduce cardiovascular impairment and even MODS during the acute and recovery phases of COVID-19." (PMID 32426374, 2020). "Additionally, several lines of evidence indicated that asiaticoside (a saponin), borneol (a terpene), catalpol (an iridoid) as other phytochemicals declined the neuronal levels of TNF-α, IL-6, TLR4, NF-κB, IL-β and IL-8, thus may be hopeful agents against neurological symptoms in COVID-19." (PMID 33708124, 2020). "Furthermore, serum concentrations of IL-10, IL-6, and TNF-α were significantly lower in patients in the disease resolution in comparison to the disease period, whereas the total number of T cells, CD4+ T cells, and CD8+ T cells was restored during the decline period of COVID-19." (PMID 32916812, 2020).
COVID-19 (continued). "While there may be a subset of patients who may potentially benefit from the use of tocilizumab, current evidence does not support the routine use of tocilizumab or other drugs that regulate host immune response (i.e., anti-IL1, anti-TNFα) in COVID-19 or non-COVID-19 sepsis." (PMID 33195334, 2020). "Not only other cytokines, e.g., tumor necrosis factor-alpha, but also white blood cells have shown correlations with CRP, underscoring that CRP elevation in COVID-19 reflects a broader pro-inflammatory milieu rather than the action of IL6 alone." (PMID 41373577, 2025). "Although none of the sera showed a significant increase in TNFA expression, the results of assaying HUVEC supernatants showed that sera from patients with severe COVID-19 significantly induced the production of TNF-α." (PMID 41583455, 2025). "We identified that only three proteins, namely TNF, SLAMF1, and CDCP1, were differentially abundant in critically ill COVID-19 patients compared to those with non-critical illness presentation." (PMID 40475767, 2025). "The evaluation of plasma levels of TNF-α, IFN-γ, and IL-10 showed that although IFN-γ levels were higher in individuals with the severe form of COVID-19 in the bivariate analysis, this result was not confirmed in the multiple logistic regression analysis." (PMID 39859379, 2025). "Upon comparison of the biomarker levels with those in control cases, it was detected that critically ill COVID-19 controls without AKI had lower levels of uSerpinA3, uKIM-1, uNGAL, TNF-α, and IL-10." (PMID 40804924, 2025). "Stool cytokine detection has been previously studied in the context of COVID-19, cirrhosis, and IBD; identifying elevated stool TNFα in IBD, but not inflammatory arthritis." (PMID 38966778, 2024). "However, the coincident involvement of TNFα/NFκB and ENaC signaling is not intrinsic to any of these candidate mechanisms, and it may be that the path to understanding the true origins of the pro-inflammatory state in the COVID-19 lung may lie elsewhere." (PMID 39043712, 2024). "Collectively, our study revealed that COVID-19-affected T2DM patients exhibited higher levels of several inflammatory mediators, including CRP, IL-6, and TNF-α in comparison to COVID-19 non-DM patients." (PMID 38675414, 2024). "Our finding that TNF-α and IFN-γ are of little importance in COVID-19 is not unprecedented; their concentrations either did not change or showed very small, insignificant increases in several previous studies." (PMID 39337495, 2024). "Similar to IL-6, IL-10, and TNF- α, CCL-3 and CXCL-13 levels were not significantly different between mild-to-moderate COVID-19 patients, recovered individuals, and healthy controls." (PMID 38646483, 2024). "Correspondingly, circulating levels of pro-inflammatory cytokines IL-6, TNF and IFN-γ, and of anti-inflammatory IL-10, were altered with respect to reference values but similar in COVID-19 and No COVID-19 patients." (PMID 37408073, 2023). "Regardless of the active role of TNF-α in promoting the host’s innate immunity, a few reports found less significant implications of TNF-α in the morbidity and mortality of COVID-19." (PMID 37047115, 2023). "While the levels of pro-inflammatory markers, such as CRP, IL-6, IL-1Ra, and TNF-α, were slightly higher, and anti-inflammatory cytokines, such as TGF-β1, were lower in COVID-19/PLWH than in those without HIV, none of these differences was significant." (PMID 37646024, 2023). "We determined that increased interleukin (IL)-6 and IL-10, and tumor necrosis factor-α and interferon gamma were not predictive of severe ANE and mortality in children with COVID-19 in this study." (PMID 37602239, 2023). "The diminished abundance of E. rectale comes with the negative correlation to C-X-C motif ligand 10 (CXCL10) and tumor necrosis factor-alpha (TNF-α), two inflammation markers that indicate the origination of immune response at the early stage of COVID-19." (PMID 37743871, 2023).
COVID-19 (continued). "In the PCA, while the non-KTRs with COVID-19 were differentiated from their controls in their IL-10, IFN-α, and TNF-α, this pattern was marked in the NGAL, sVCAM-1, and IL-8 of the KTRs." (PMID 38005844, 2023). "For instance, the plasma levels of several cytokines, including MCP-1 and TNF-α, were shown to be higher in ICU than non-ICU COVID-19 patients." (PMID 37081872, 2023). "This survey revealed that none of the patients receiving anti-TNFα antibodies, other biologic agents, or JAK inhibitors experienced severe COVID-19." (PMID 39131552, 2023). "Severe COVID-19 patients that developed AKI had increased levels of proinflammatory cytokines (e.g., IFN-γ, IL-1β, IL-8 and TNF-α) compared with non-severe patients." (PMID 37251383, 2023). "Symptomatic patients with COVID-19 requiring admission to the intensive care unit (ICU) were shown to have elevated levels of IP-10, MCP-1, and TNF-α compared with patients with less severe symptoms not requiring ICU admission." (PMID 37376437, 2023). "In a retrospective study, LMW heparin was shown selectively to reduce plasma IL-6 concentrations, but not concentrations of IL-2, TNF-α, IL-4, IL-10 or IFN-γ in patients with COVID-19." (PMID 37111341, 2023). "In addition, we showed that the cytokines IFN-γ, IL-2, IP-10, IL-1β, IL-6, IL-8, and TNF could discriminate the status of SARS-CoV-2 infection or exposition, and also it highlighted the high levels of pro-inflammatory IL-1β and IL-6 in long-COVID-19 when compared to the unexposed group." (PMID 37018291, 2023). "Remarkably, COVID-19 patients requiring intensive care unit (ICU) admission presented higher levels of CCL2, CXCL10, IL-2, IL-7, IL-10 and TNF-α than non-ICU patients, hinting the linkage between the cytokine storm and COVID-19 deterioration." (PMID 37251383, 2023). "Results showed that compared with patients with less severe infections without Intensive Care Unit (ICU), patients with COVID-19 with ICU had higher concentrations of CXCL10, CCL2, and TNF-α." (PMID 35911765, 2022). "Furthermore, TNFα inhibitors may even be protective of severe COVID-19 relative to other treatments or no treatment at all, and biological treatment does not seem to have a significant impact on the response and safety of vaccines in patients with psoriasis treated with biologicals." (PMID 36079026, 2022). "MSCs were used in several pilot studies for treatment of severe COVID-19, demonstrating their efficiency by patient clinical improvement, better oxygenation and decreased inflammatory markers (CRP, IL-6, TNF-α, procalcitonin) with no observed adverse effects." (PMID 36499448, 2022). "Six of seven patients had received anti-TNFα antibodies and there was no worsening of disease activity in seven IBD patients with COVID-19 post vaccination despite the discontinuation of IBD drugs." (PMID 35089397, 2022). "Systems biology studies have shown that proinflammatory cytokines, IL-6, IL-1β, and TNF-α, originating from SARS-CoV-2 infected lungs, but not from the peripheral blood cells, contribute to COVID-19 severity." (PMID 36298628, 2022). "In the study, the results showed that the levels of pro-inflammatory cytokines (IL-2, IL-4, IL-6, TNF-α, and IFN-γ) were not different between mild, moderate, and severe/critical groups of children with COVID-19." (PMID 36294306, 2022). "However, this particular research confirmed that TNF-α/NF-κβ/renalase axis exhibits favorable outcomes, summarized as reduced cell cytotoxicity (validated as reduced LDH levels), and apoptosis (measured as decreased caspase-3 activity), a phenomenon that may be of a great advantage in COVID-19." (PMID 36132227, 2022). "With the exception of IL-1β and TNF-α, HIV/COVID-19 patients showed similar levels of IL-6 and IL-8 than those observed in HIV patients without COVID-19." (PMID 35891555, 2022). "Compared to non-hospitalized COVID-19 patients, severe cases showed increased cytotoxic Tfh cells which manifested high levels of IFN-γ, IL-2, and TNF-α." (PMID 36505489, 2022).
COVID-19 (continued). "We found that COVID-19 plasma exosomes and LPS stimulated significant production of IL-6, IL-8, and TNF-α in CD3+ lymphocytes compared with those treated with non-COVID plasma exosomes, establishing that PBMC responded to COVID-19 plasma exosomes." (PMID 36526691, 2022). "In Non-SOT COVID-19 patients, we observed 6 (IL-13, IL-10, IFN-γ, IL-12p70, MCP-2, IL-6) and 9 (IL-16, IL-13, TNF-α, IL-6, IL-18, IL-15, MIP-1α, IL-2Ra, IL-8) cytokine correlations with monocyte and neutrophil derived cfDNA, respectively." (PMID 35075453, 2022). "COVID-19 ICU patients had significantly higher levels of the proinflammatory cytokines CXCL1, IL-1β, IL-6, MCP-1, and TNF-α compared to the non-COVID group." (PMID 35502320, 2022). "Like COVID-19 vaccines, HBV and Influenza vaccines among patients receiving anti-TNF therapy, especially infliximab (with or without combination therapy), exhibited lower seroprotective levels." (PMID 35860742, 2022). "Non-pregnant patients with severe COVID-19 have been found to have greater levels of IL-2, IL-6, IL-7, IL-10, IP-10, MCP-1, TNF-α, macrophage inflammatory protein 1 alpha, and granulocyte-CSF than those with mild and moderate infections." (PMID 36383608, 2022). "Moreover, it is important to demonstrate that CBD does not increase mortality among COVID-19 participants, as observed in infected pneumococcal meningitidis animals, with CBD administration, showing an increase in survival associated with a decrease in TNF-α expression." (PMID 35401543, 2022). "TNF-α, MCP-1 and IP-10 (but not IL-6 or IL-8) were significantly higher in both COVID-19 groups than the control group." (PMID 33921604, 2021). "COVID-19 patients that require ICU admission have higher blood concentrations of IL-6, CXCL10, CCL2 and TNF-α as compared to patients with milder disease that does not require ICU admission." (PMID 33968010, 2021). "Among routine markers of inflammation, PCT and TNF-α, but not CRP, IL-6 or ferritin, were higher in COVID-19 patients on MV compared to those not on MV." (PMID 33058027, 2021). "While TNFα does not signal through JAK-STAT proteins, it is discussed here because it is found elevated in COVID-19 patients requiring intensive care." (PMID 34326843, 2021). "We found that the serum levels of multiple pro-inflammatory cytokines or biomarkers, including IL-6, IL-10, IL-8, TNF-α, IL-1β, IL-2R, ferritin, hs-CRP and procalcitonin were substantially elevated in non-survivors with COVID-19." (PMID 34521370, 2021). "We also noted that, in the COVID-19-naive population, the frequency of AIM+IL-2+CD8+ T cells was greater among the older than among the younger, but frequencies of IFNγ+, TNFα+, or triple+ CD8+ T cells were not different." (PMID 34868051, 2021). "A recent report demonstrated the secretion of Granzyme B by CD4+ and CD8+ T cells isolated from COVID-19 patients although without the co-expression of CD107 and TNFα, suggesting an exhaustion state of these cytotoxic cells." (PMID 34436366, 2021). "Unlike increased levels of TNFα, IL-6, IL-8, IL-10, CXCL8, and IP-10 observed in H1N1 infected pregnant patients, COVID-19 pregnant patients showed relatively lower expressions of pro-inflammatory and anti-inflammatory cytokines." (PMID 34012458, 2021). "Correlation between TNF-α and sTNFR and other factors in ICU and non-ICU COVID-19 patients and healthy subjects." (PMID 33968010, 2021). "Since we showed that IL-7 treatment augmented perforin levels without significantly increasing TNF-α and IFN-γ production, this may indicate that IL-7 therapy might enhance the functionality of MAIT cells without contributing to the cytokine storm associated with severe COVID-19." (PMID 34238985, 2021). "We also noted that, in the COVID-19-naive population, the frequency of AIM+IL-2+CD8+ T cells (but not IFNγ+ or TNFα+CD8+ T cells) was greater among the older subjects compared with the young group." (PMID 34868051, 2021).